ENSG00000252458
Synonyms: LOC124900203
Gene: Small nucleolar RNA gene on chromosome 5 (159,230,194 to 159,230,322, forward strand). Ensembl gene ENSG00000252458.
Gene Ontology:
Biological process: RNA processing
Cellular component: nucleolus
Homologues: Orthologues: mouse Gm22661 (64% identical), rat LOC120097214 (63% identical), mouse Gm22331 (62% identical), mouse Gm23877 (59% identical). Paralogues in human: SNORA68 (84% identical), SNORA68B (84% identical).